IL6 (interleukin 6)
Diseases named in the same sentence as IL6 in open-access papers (continued):
Sharing a sentence is not in itself a finding about the gene and the disease.
tumor (continued). "Although IL-6 inhibition reduces the constitutive production of inflammatory mediators, it has no impact on tumor growth or cell survival because of the lack of stromal reaction." (PMID 29930760, 2018). "Strikingly, IL-6 knockout robustly induced extensive necrosis and leukocyte infiltration, possibly due to its negative effects on macrophage-mediated tumor immunity." (PMID 29422647, 2018). "Torsvik and Bjerkvig reviewed MSCs signaling involved in cancer progression and concluded that MSCs-secreted IL6 could promote initiation and EMT/metastasis of tumor via activation of JAK/STAT pathway." (PMID 29615660, 2018). "There has been no previous study regarding the association between DII and tumor size or lymph node status, but DII has been shown to associate with inflammatory cytokines such as IL-6 and TNF-α." (PMID 30111758, 2018). "In addition, CAFs exhibit increasing secretion of IL-6 and IL-8, promoting stemness, EMT, chemoresistance, and tumorigenicity of tumor cells." (PMID 29335551, 2018). "Tumor cells are reported to have elevated levels of chemokine (C-X-C motif) ligand 1 (CXCL1), a chemokine that plays a role in inflammation and tumorigenesis, as well as interleukin-6 (IL-6), a cytokine that prevents immune dendritic cell development." (PMID 29342862, 2018). "IL-1β, IL-6 and RANK Ligand also amplify inflammation and promote tumor growth and dissemination." (PMID 30038719, 2018). "Indeed, exosomes expressing HSP72 and HSP105 can trigger a TLR2- and TLR4-dependent IL-6 release from conventional DCs and a consequent MMP9 expression in tumor cells with enhanced invasion and metastasis." (PMID 30200242, 2018). "Treatment with cisplatin only did not reduce IL-6 levels when compared with the tumor control group, whereas IL-6 levels were significantly ameliorated by the treatments with antrodan only." (PMID 29794990, 2018). "Their application may hold promise in treatment of bone-resident cancers if more developed (e.g., bi-specific mAbs against tumor cells and IL-6, or against RANKL and IL-6) therapies can be developed to increase their efficacy." (PMID 30671025, 2018). "We further tested whether increased IL-6 and CCL2 expression in tumor epithelial cells is a direct result of increased cellular stress in response to IGF-1R inhibition." (PMID 30458886, 2018). "Previously published data regarding the role of IL-6 and IL-10 in BC mostly investigated levels in serum or in whole tissue extracts without focusing on tumour tissue localisation." (PMID 29256156, 2018). "In some cases, the expression of ABC transporters and the consequent acquisition of a chemoresistant phenotype stems from OXPHOS-driven inflammatory reactions culminating in the secretion of interleukin 6 (IL6) and tumor necrosis factor (TNF) into the tumor microenvironment." (PMID 29219147, 2018). "This indicates that IL-6 is not the major signaling pathway in the intestinal epithelium promoting intrinsic tumor growth via STAT3." (PMID 30591653, 2018). "On the other hand, a wide range of pro-inflammatory factors, e.g., PGE2, TNF, IL-1β, IL-6, S100A8, S100A9, IFNγ, IL-4, IL-10, and IL-13 secreted by cancer cells and leukocytes residing in the tumor inhibit the differentiation of myeloid progenitors and enhance their suppressive capacity." (PMID 30349530, 2018). "MiR-203 as a tumor suppress gene, studies have found hepatic over-expression of miR-203 could facilitate the initiation of the liver by targeting SOCS3 through IL-6/STAT3 signaling pathway." (PMID 29670525, 2018). "Primarily, IL-6 activates signal transducer and activator of transcription 3 (STAT3) signaling thus promotes tumor cell proliferation and enhances cell invasiveness in cancers, which is in line with the constitutive activation of STAT3 in RCC, especially in metastatic disease." (PMID 29717134, 2018).
tumor (continued). "We next investigated whether combinatorial blocking of IL-6/STAT3 and PI3K/Akt pathways would have an effect on tumor growth and response to chemotherapy." (PMID 29930760, 2018). "The tumours grew equally well in the absence of IL-6, and at day 23 tumours were excised and analysed." (PMID 30054470, 2018). "While IL-6 blockade in male LR/Stat3Δ/Δ mice reduces lung tumorigenesis, inhibition of estrogen receptor signaling in female mice augments K-ras mutant oncogenesis and reprograms lung TME toward a pro-tumor phenotype." (PMID 30389925, 2018). "Earlier reports indicated that IL-6 and TNF-α have a tumor-promoting effect." (PMID 28969049, 2017). "We postulate that the release of cell debris from the tumor to the blood as a result of the hyperthermic tumor treatment might lead to a systemic release of cytokines (e.g. IL-1, TNF-α, IL-6)." (PMID 28761146, 2017). "Researches showed that inflammatory mediators, such as interleukin 6 (IL-6), Toll-like receptor (TLR), signal transducer and activator of transcription 3 (STAT3), and nuclear factor-κB (NF-κB), are critical in the transformation from inflammation to tumor." (PMID 29190960, 2017). "In addition, IL-6, IL-10, and VEGF activate STAT3 in tumor infiltrating immune cells, providing a feed forward mechanism for STAT3 activation in the tumor microenvironment." (PMID 28611673, 2017). "Like TNF-α, IL-6 facilitates tumor development by promoting the conversion of non-cancer cells into tumor stem cells in vitro via Oct4 gene upregulation expression through IL-6R/JAK/STAT3 signaling." (PMID 28030810, 2017). "It is found that the anti-tumor effect of APS on H22 tumor-bearing mice might be related to its ability to enhance the expression of IL-1, IL-2, IL-6 and TNF-α and decrease of IL-1040." (PMID 28303957, 2017). "Since INOS, COX-2, and, TNF-alpha, and, IL-6 are important factors in the NF-κB pathway, we detected whether PPS could enhance immunostimulatory activities in the tumor microenvironment through regulating these factors and pathways." (PMID 29155869, 2017). "We first analyzed IL-6 expression after TKI treatment in RCC cells and RCC tumor specimens." (PMID 28903416, 2017). "In addition, IL-6, STAT3 and HIF1 protein levels in Hep2-CSC were consistently and significantly increased as compared with that from Hep2 cells or Hep2-derived tumor tissue (p < 0.001)." (PMID 28878571, 2017). "Interestingly, number of EMT/CSC-related factors such as IL1a, IL6, NOS2 and TGFb129, 35, 36, were highly expressed in BM or tumour-derived mMDSCs and also further enhanced the expression of these genes in tumour cells upon co-culture." (PMID 28382931, 2017). "Furthermore, the treatment of LPS-CuS with laser irradiation promoted up-regulation of IL-6, IL-12p40, and TNF-α mRNA levels in tumor drLN." (PMID 29285274, 2017). "Additionally, immunohistochemical tumor CRP expression and serum concentrations of interleukin (IL)-6 and IL-1β were measured." (PMID 28514756, 2017). "Interestingly, IL-6, CCL2, and periostin were recently demonstrated to promote M2 macrophage polarization, and thus contribute to tumor growth." (PMID 28969635, 2017). "In particular, we demonstrate that blockade of the IL-6/STAT3 axis eliminates FGF19-induced tumour formation without compromising the metabolic functions of FGF19 in regulating bile acid, glucose and energy homoeostasis." (PMID 28508871, 2017). "The cytokines like IL-6 and TNF-α may activate pro-tumor pathways like STAT3 to promote cellular proliferation and thereby initiate carcinogenesis." (PMID 28360909, 2017). "For example, it has been reported that TGF-β is the major inducer of the interleukin-6 (IL-6) and vascular endothelial growth factor (VEGF), and the increased production of TGF-β is followed by the increased IL-6 and VEGF secretion related to tumor cell proliferation." (PMID 28959347, 2017).
tumor (continued). "To this end, we previously established a 3D mono and co-culture model with lung, breast and pancreatic cancer cell lines and tumor-associated fibroblasts and identified soluble factors such as IL-6, CCL-2 and GM/M-CSF in co-culture supernatants that influence tumor growth and progression." (PMID 28750018, 2017). "Moreover, paracrine IL-6 signaling between DCIS cells and CAFs promotes tumor cell growth and migration in part through cathepsin B-mediated ECM degradation." (PMID 28506312, 2017). "Furthermore, IL6 and CCL2 are able to support tumor growth, EMT, stem cell migration, and finally treatment resistance." (PMID 29029509, 2017). "Conversely, cancer cachexia is associated with an increase in blood levels of C-reactive protein, cytokines (interleukin 1b, interleukin-6, TNF-α, and leukemia inhibitor factor, LIF) and other tumor derived factors like lipid mobilizing factor (LMF) and protein mobilizing factor (PMF)." (PMID 28337150, 2017). "Most of the bacteria (for instance B. xylanisolvens, Paraprevotella clara, Prevotella timonensis) were positively relating with anti-inflammatory/tumor markers (e.g. Trem-2, MR, arginase-1, TNF-α) and negatively correlating with pro-inflammatory/tumor markers (e.g. IL-12, IL-6 and iNOS)." (PMID 28970547, 2017). "Minimal IL-6 production was observed in tumor cells (CD45- cells) or non-myeloid (CD11-) immune cells." (PMID 29207662, 2017). "SUP3 was shown to enhance cross-presentation by CD8+ cDCs in vitro, up-regulate the expression of CD40 and CD86 co-stimulatory molecules and induce production of IL-6 and TNFα in DC, culminating in an antigen-specific CD8+ T cell response and increased immunization against tumor challenge." (PMID 29050360, 2017). "Cytokine analysis of serum obtained from treated mice demonstrated a surge in IFN-γ, IL-6, and CXCL10 concentrations prior to peak T cell expansion, which also returned to background levels post tumor elimination and following contraction of T cell density in the lungs to background levels." (PMID 29085043, 2017). "In the tumor microenvironment, MSCs also secrete a panel of growth, immunomodulatory, and signaling molecules, such as CCL5, CCL2, TGF-β, VEGF, IL-6, and IL-10, which may play role in angiogenesis." (PMID 29268703, 2017). "It is tempting to speculate that OGR1 signaling and subsequent release of IL-6 and IL-8 by OGR1-expressing cells may contribute to neoangiogenesis to feed the growing tumor and provide oxygen to perivascular tumor regions." (PMID 29245949, 2017). "In terms of tumor apoptosis, IL-6 promoted the apoptosis of HCCLM3 cells without any treatment and was presented in a time-dependent manner." (PMID 29100435, 2017). "Therefore, our present study was conducted to study the exact effect of IL-6 on tumor cell proliferation, apoptosis, invasion, and related biological HCC cell behavior based on the knock-out of IL-6 by TALEN." (PMID 29100435, 2017). "In addition, STAT3, as the major effector of IL-6/GP130, is classified as an oncogene contributing to oncogenic transformation in cultured cells and tumor formation in nude mice." (PMID 28672024, 2017). "GP130 is emerging as attractive and promising therapeutic target for cancer therapy, because accumulating data demonstrated IL-6/GP130 signaling plays critical role in tumorigenesis, tumor proliferation, metastasis, and chemoresistance in multiple types of tumors." (PMID 28672024, 2017). "The concentrations of TNF-α and IL-6 in the APS group had no obvious difference from those in the NS group of the MyD88−/− tumor-bearing mice (P > 0.05)." (PMID 28303957, 2017). "IL-6 is also a growth factor that drives proliferation in several tumor types, and high serum IL-6 levels correlate with a negative prognosis." (PMID 28100773, 2017). "These pathways were not enriched in the HepG2 tumor sample, although four were increased in the HepG2 cell sample (TNFα signaling via NFκB, allograft rejection, IL-6/JAK/STAT3 signaling, inflammatory response)." (PMID 29259231, 2017).
tumor (continued). "The ELISA assay indicated that IL-6 knock-out could down-regulate IL-33 and VEGF-A secretion, which may restore M1 phenotype and inhibit tumor angiogenesis, growth, and recurrence." (PMID 29100435, 2017). "TNF-α, and IL-6 are produced in the microenvironment of the tumor as a result of the nonspecific inflammatory response, which appears to increase c-MET expression." (PMID 28404966, 2017). "IL-6 has no direct effect on cell proliferation and invasion but promotes tumor cell apoptosis in vitro study." (PMID 29100435, 2017). "IL-6 and IL-8 released from myofibroblasts could also trigger the upregulation of S100A8/A9 in tumor-infiltrated myeloid cells." (PMID 29379499, 2017). "This positive loop established between immune and stromal components is also supported by tumour cells, which participate to this cross-talk through secretion of MCP-1 and IL-6, thereby facilitating both monocyte recruitment and again differentiation into M2 macrophages." (PMID 27223431, 2017). "As seen for inflammatory genes such as Il1b and Il6, also the expression of Trem1 was highly increased in Trem1+/+ tumors as opposed to matched tumor-free colonic mucosa." (PMID 29093489, 2017). "Finally, based on tumor status, there were significant changes in proinflammatory cytokines (IFN-γ, IL-6, IL-5, IL-2, IL-10) and a growth factor (FGF-basic)." (PMID 27893434, 2017). "Therefore, we further analyzed the percentages of IL-17A-, IL-6-, IFN-γ-, IL-4-, granulocyte macrophage colony stimulating factor (GM-CSF)- and IL-1β-producing cells in tumor-infiltrating cell populations from mice administered L-4F or Sc-4F." (PMID 29245934, 2017). "In our hands, blocking TNFα or IL-6 was unable to prevent the delipidation of adipocytes induced by tumor cells in our co-culture system, suggesting that they are not involved and/or sufficient to explain this paracrine and “acute” delipidation." (PMID 28915700, 2017). "In all the tumor cells overexpressing MAP17, we detected a clear increment in the expression of IL-6, while NFAT2 was clearly increased in HeLa cells with small changes in the other considered cell models, showing that MAP17 has a real role as an inflammatory inducer." (PMID 29228712, 2017). "Bazedoxifene was found to disrupt IL-6 and GP130 interaction and STAT3 activation, therefore, we investigated whether Bazedoxifene blocks tumor invasion and angiogenesis." (PMID 28672024, 2017). "Immunohistochemical examination confirmed the absence of IL-6 and negligible activation of mTOR signaling in the tumor cells of non-treated mice." (PMID 28903416, 2017). "Our results suggest that in the absence of DNA damage, DNMT1, and JAK/STAT signaling, IL-6 release most likely plays a role in differentiation, as observed by reduced CK-5 expression, and elicits anti-tumor activity in MIBC cells." (PMID 29242529, 2017). "We found that SLE altered the expressions of some genes related to tumor immune evasion (e.g. IL-6, IL-17, STAT1, TNF-α, CD45, MHCII) (Data not shown)." (PMID 28596565, 2017). "STAT3 has been characterized as one of the major drivers of GBM, contributing to the maintenance of stemness and a mesenchymal phenotype via the IL-6/glycoprotein 130 (GP130)/STAT3 or EGF receptor (EGFR)/JAK2/STAT3 axis and leading to chemo- and radiation resistance of the tumor." (PMID 29340087, 2017). "In contrast to in vitro data suggesting an inverse relationship between HBx–NF-κB–SHP2 activity and STAT3 signaling, HCC-surrounding non-neoplastic tissues exhibited increased IL-6–JAK–STAT3 signaling compared with matched tumor tissues." (PMID 28460481, 2017). "In HPV-driven carcinogenesis, IL-6-induced JAK/STAT3- and C/EBPβ-driven stromal inflammation may play a key role in promoting tumor progression." (PMID 28895886, 2017). "Tumor-bearing mice neither showed elevated serum levels of the inflammatory cytokines IL-6 and IL-1β, known activators of hepcidin expression nor increased hepatic hepcidin mRNA levels (Hamp1)." (PMID 29167669, 2017).
tumor (continued). "Tumor-associated macrophages (TAMs), which secrete immunosuppressive molecules such as IL-6 and TGF-β that dampen T-cell responses to MHC-presented tumor antigen, are found in the tumor microenvironment of a variety of cancers, including renal cell carcinomas and neuroblastoma." (PMID 29326711, 2017). "In C57BL/10J (TLR4+/+wild-type) and C57BL/6J (MyD88+/+wild-type) tumor-bearing mice, the tumor apoptosis rate, immune organ indexes and the levels of TNF-α, IL-1β and IL-6 in blood increased and the tumor weight decreased by oral administration of APS for 25 days." (PMID 28303957, 2017). "Conversely, in THP-1 cells, the decrease in IL-6 and IL-1β concentrations by CLE may diminish cytokine induced tumour immunosuppressive activity and cancer progression." (PMID 28764778, 2017). "Within the tumor microenvironment, TAMs are forced forwards M2 phenotypes by GBM cells via secreting a wide variety of factors such as IL10, IL4, IL6, M-CSF, macrophage inhibitory factor (MIF), TGFβ, and prostaglandin E2 (PGE2), and subsequently support tumor growth and invasion." (PMID 29132376, 2017). "In the breast TME, tumor and stromal cells stimulate cytokine-mediated p38MAPK signaling that increases expression of pro-angiogenic and pro-invasive factors such as VEGFA, IL8, IL6, HBEGF, and Fibronectin." (PMID 28977919, 2017). "Accordingly, we found that (+)-JQ1 administration significantly (p < 0.0001, one-way ANOVA) reduced IL6 circulating levels, which were significantly (p < 0.0001, one-way ANOVA) elevated in tumor-bearing mice treated with either vehicle or (−)-JQ1, when compared to control mice." (PMID 29167426, 2017). "Recent data indicate that endocrine dysfunction in patients with MG may be related to the production of growth factors as well as of cytokines such as IGFBP-2 and IGFBP-3, VEGF, IL-1β, IL-6, and TNF-α by tumor cells or their microenvironment." (PMID 28740334, 2017). "Although not investigated here, it is possible that the elevated IL-6 levels we observed in tumor pericytes leads to vessel activation and pericyte detachment via Ang-2 in the present microvascular model." (PMID 28878242, 2017). "It is possible that IL-6 expression might be regulated by TGF-β signaling in GBC-PC, attenuating cell proliferation and other neurovascular functions that also affect the tumor progression." (PMID 28978142, 2017). "Among these cytokines, IL-6 had the highest concentration, indicating that IL-6 secreted by CD4+ T cells may play a role in the interaction with tumor cells." (PMID 28846080, 2017). "Then, we showed that IL-6 secreted by CD4+ T cells can trigger EMT in ccRCC, which may be the source of α-SMA (+) cells, and also enhanced the metastatic ability of tumor cells." (PMID 28846080, 2017). "EC-derived IL-6 induces phosphorylation of STAT3 in tumor cells and promotes tumor growth." (PMID 28978186, 2017). "Both the IL-6 and TGF-β are important cytokines initiating EMT in tumor microenvironment." (PMID 27992365, 2017). "We show that the tumor-suppressive actions of MEPs are mediated by PAI-1, uPA and its receptor, uPAR, and are sustained even in the presence of the CAFs, which themselves enhance DCIS tumorigenesis via IL-6 signaling." (PMID 28506312, 2017). "Collectively, our data indicates that, in addition to controlling tumor-specific proliferation, the IL-17RC-A20 axis has a regulatory role in selectively repressing production of pro-inflammatory cytokines, including IL-6 and GM-CSF, but not CXCL1." (PMID 28562353, 2017). "When inflammation occurs, tumor cells, macrophages, and other tumor infiltrating immune cells possess high reactive oxygen species (ROS), and secrete chemokines and cytokines such as IL-6, tumor necrosis factor (TNF)-α, IL-1β, IL-10, and transforming growth factor (TGF)-β to tumor microenvironment." (PMID 28629173, 2017). "Similarly, the level of IL-1β, IL-6 and TNF-α was also increased by APS in EAC tumor-bearing mice in vivo." (PMID 28303957, 2017).